ENSG00000272162 (novel transcript, TMEM14B-SYCP2L readthrough)
Gene: Protein-coding gene on chromosome 6 (10,747,794 to 10,930,423, forward strand). Ensembl gene ENSG00000272162.
Genetic constraint (gnomAD): Missense variants: 31 observed, 39.33 expected, observed/expected ratio (o/e) 0.79, 90% interval 0.59 to 1.06. Synonymous variants: 16 observed, 14.69 expected, observed/expected ratio (o/e) 1.09, 90% interval 0.74 to 1.64.